SOX11 (SRY-box transcription factor 11)
Description:
Transcription factor that acts as a transcriptional activator. Binds cooperatively with POU3F2/BRN2 or POU3F1/OCT6 to gene promoters, which enhances transcriptional activation (By similarity). Acts as a transcriptional activator of TEAD2 by binding to its gene promoter and first intron (By similarity). Plays a redundant role with SOX4 and SOX12 in cell survival of developing tissues such as the neural tube, branchial arches and somites, thereby contributing to organogenesis (By similarity).
Synonyms: CSS9; IDDMOH; MRD27
Tractability: Antibody: its Gene Ontology location is reachable by antibodies, with high confidence. PROTAC: ubiquitination databases record sites on it.
Gene: Protein-coding gene on chromosome 2 (5,692,384 to 5,701,385, forward strand). Ensembl gene ENSG00000176887.
Subcellular location: Nucleus
Subcellular location (Human Protein Atlas): Nucleoplasm; Plasma membrane
Gene Ontology:
Molecular function: RNA polymerase II cis-regulatory region sequence-specific DNA binding; DNA-binding transcription activator activity, RNA polymerase II-specific; DNA-binding transcription factor activity; DNA-binding transcription factor activity, RNA polymerase II-specific; transcription cis-regulatory region binding; cis-regulatory region sequence-specific DNA binding; DNA binding; sequence-specific double-stranded DNA binding
Biological process: negative regulation of gene expression; negative regulation of glial cell proliferation; negative regulation of lymphocyte proliferation; negative regulation of transcription by RNA polymerase II; neuron differentiation; positive regulation of gene expression; positive regulation of neuron differentiation; positive regulation of ossification; positive regulation of osteoblast differentiation; positive regulation of stem cell proliferation; positive regulation of transcription by RNA polymerase II; regulation of transforming growth factor beta receptor signaling pathway; brain development; camera-type eye morphogenesis; closure of optic fissure; cornea development in camera-type eye; embryonic digestive tract morphogenesis; embryonic skeletal system morphogenesis; eyelid development in camera-type eye; glial cell proliferation; hard palate development; lens morphogenesis in camera-type eye; lung morphogenesis; negative regulation of transcription regulatory region DNA binding; nervous system development; and 16 more
Cellular component: nucleoplasm; nucleus; chromatin
Genetic constraint (gnomAD): Loss-of-function variants: 5 observed, 9.15 expected, observed/expected ratio (o/e) 0.55, 90% interval 0.28 to 1.15. That is too few expected variants to judge how well the gene tolerates losing a copy. Missense variants: 492 observed, 590.92 expected, observed/expected ratio (o/e) 0.83, 90% interval 0.77 to 0.9. Synonymous variants: 363 observed, 274.59 expected, observed/expected ratio (o/e) 1.32, 90% interval 1.21 to 1.44.
Gene-disease validity (ClinGen):
ClinGen rates the evidence that SOX11 causes each of these diseases.
SOX11-related complex neurodevelopmental disorder with or without congenital anomalies (autosomal dominant): Definitive. An autosomal dominant disorder caused by pathogenic variation in SOX11 characterized by developmental delay, impaired intellectual development and microcephaly.
Homologues: Orthologues: chimpanzee SOX11 (99% identical), macaque SOX11 (99% identical), pig SOX11 (96% identical), rabbit SOX11 (90% identical), dog SOX11 (89% identical), guinea pig SOX11 (78% identical), mouse Sox11 (78% identical), rat Sox11 (76% identical), tropical clawed frog sox11 (61% identical), zebrafish sox11a (59% identical), Drosophila melanogaster Sox14 (22% identical), Drosophila melanogaster Sox21a (17% identical), and 3 more. Paralogues in human: SOX4 (41% identical), SOX12 (30% identical), SOX9 (20% identical), SOX10 (20% identical), SOX3 (19% identical), SOX7 (19% identical), CFAP65 (18% identical), SOX8 (18% identical), SOX1 (18% identical), SOX17 (18% identical), SOX18 (18% identical), SOX2 (18% identical), and 8 more.
Diseases named in the same sentence as SOX11 in open-access papers:
SOX11 is named in the same sentence as 220 diseases in open-access papers, as found by Europe PMC text mining. Sharing a sentence is not in itself a finding about the gene and the disease. The quoted sentences say what the papers report.
mantle cell lymphoma (65 papers, 2010 to 2025). Mantle cell lymphoma is a rare form of malignant non-Hodgkin lymphoma affecting B lymphocytes in the lymph nodes in a region called the ``mantle zone''. "The study found that Sox11 expression in mantle cell lymphoma is associated with DNA methylation levels, which can inhibit tumour cell proliferation." (PMID 39039706, 2024). "SOX11 also contributes to nervous system development, neurogenesis and oncogenesis, as its mutations have been associated with the emergence of mantle cell lymphoma." (PMID 37761179, 2023). "In the cases with blastoid morphology, two main differential diagnoses need to be ruled out, namely B-lymphoblastic lymphoma/leukemia (positive for TdT and/or CD34) and the blastoid variant of mantle cell lymphoma (positive for Bcl-1/cyclin D1 and/or SOX11)." (PMID 33322508, 2020). "SOX11 mutations and overexpression have been associated with autosomal dominant mental retardation, coffin-siris syndrome, mantle cell lymphoma, and malignant glioma." (PMID 26949534, 2016). "Knockdown of sox11 in the mantle cell lymphoma cell line, Grant 519 caused a significant reduction in caspase-6 RNA." (PMID 26505998, 2015). "The transcription factor SOX11 is of diagnostic and prognostic importance in mantle cell lymphoma (MCL) and epithelial ovarian cancer (EOC), respectively." (PMID 22738398, 2012). "SOX11 overexpression has been associated with aggressive behavior of mantle cell lymphomas (MCL)." (PMID 36509891, 2023). "Moreover, previous studies have shown SOX11 to be a useful diagnostic marker for mantle cell lymphoma." (PMID 34980027, 2022). "The neural transcription factor SOX11 is a novel diagnostic antigen for mantle cell lymphoma (MCL)." (PMID 20624318, 2010). "In mantle cell lymphoma (MCL) SOX11 is highly expressed and is a diagnostic biomarker that distinguishes MCL from other mature B-cell lymphomas." (PMID 26894864, 2016). "Nuclear overexpression of SOX-11 has been identified as a highly specific marker for mantle cell lymphoma (MCL)." (PMID 39258061, 2024). "Mantle cell lymphoma (MCL) is an incurable B-cell neoplasm characterized by an aggressive behavior, short responses to conventional therapies and SOX11 overexpression, which is associated with aggressive disease features and inferior clinical outcome of patients." (PMID 38570586, 2024). "Sox11 has also been shown to drive mantle cell lymphoma (MCL) progression, with other studies have shown it to play a similar oncogenic role in melanoma and breast cancer." (PMID 39039706, 2024). "SOX11 is also almost constantly positive in mantle cell lymphoma and in occasional cases of diffuse large B-cell lymphoma, the most common subtype of primary CNS lymphoma." (PMID 37568909, 2023). "In SOX11-positive mantle cell lymphoma, increased tumor angiogenesis and higher levels of pro-angiogenic factors, including angiopoietin-1 and -2 and fibroblast growth factor-1, were observed." (PMID 37391758, 2023). "miR-132-3p has been registered to directly target SOX11 to inhibit mantle cell lymphoma progression." (PMID 36785792, 2023). "As a positive control, SOX11 nuclear staining was identified in 85% (46/54) of mantle cell lymphomas, which is consistent with previous reports." (PMID 34996493, 2022). "Consistent with the observations in previous reports, we detected significant upregulation of CCND1 and SOX11 mRNAs in mantle cell lymphoma cases." (PMID 36359790, 2022). "SOX11 was reported to be highly expressed in breast cancer, mantle cell lymphoma, epithelial ovarian cancer and hepatocellular carcinoma, while it was expressed at low levels in nasopharyngeal carcinoma, prostate cancer, gastric cancer (GC) and bladder cancer." (PMID 36551589, 2022). "For example, a high level of SOX11 mRNA can be detected in many types of tumors, including breast cancer, mantle cell lymphoma, epithelial ovarian cancer and hepatocellular carcinoma." (PMID 36551589, 2022).
mantle cell lymphoma (continued). "Except for MMs, overexpressed SOX11, as an indicator of aggressivity, was reported in mantle cell lymphoma, basal-like breast cancer, solid pseudopapillary neoplasm of the pancreas, and neuroendocrine tumors of the lung." (PMID 33801642, 2021). "Biomarkers, including CD5, cyclin D1 and SOX-11, are useful for the differential diagnosis of mantle cell lymphoma from other B-cell NHLs." (PMID 34442137, 2021). "The subcellular localisation of SOX11 can be informative for cancer classification since high SOX11 mRNA levels and detection of the nuclear protein are reliable markers of mantle cell lymphoma." (PMID 32909943, 2020). "Characteristics of studies reporting SOX11 immunohistochemistry in mantle cell lymphoma and other lymphoproliferative diseases." (PMID 31714947, 2019). "SOX11 is a transcription factor that plays an important role in embryonic neurogenesis and is overexpressed in central nervous system malignancies and mantle cell lymphomas." (PMID 30947262, 2019). "A number of studies have revealed that SOX11 promotes tumor progression in mantle cell lymphoma (MCL) as well as in melanoma and breast carcinoma." (PMID 30922366, 2019). "SOX11’s subcellular localization is considered a prognostic marker in mantle cell lymphoma, in which nuclear localization of SOX11 suggests good prognosis while cytoplasmic localization is associated with shorter survival." (PMID 29973868, 2018). "Expression of SRY [sex-determining region Y]-box11 (SOX11) is specific to mantle cell lymphoma (MCL) and contributes, in conjunction with immunoglobulin variable heavy chain gene mutation status, to the identification of two forms of this disease." (PMID 29484276, 2018). "Even though little is known about the role of Sox11 in immune cells, its overabundance is now well documented in mantle cell lymphoma, a subtype of B-cell lymphomas." (PMID 29209164, 2017). "In contrast, knockdown of Sox11 in mantle cell lymphoma cell lines actually increases cell proliferation and promotes tumorigenesis when injected into nude mice." (PMID 22536405, 2012). "In particular, SOX11 is highly expressed in mantle cell lymphoma (MCL), acute lymphoblastic leukemias (ALL) and in some Burkitt lymphomas (BL)." (PMID 21738649, 2011). "Among these genes, DBN1, SETMAR and HIG2 were found to be significantly correlated to SOX11 expression in two cohorts of primary mantle cell lymphomas." (PMID 21124928, 2010). "Additionally, the endogenous SAMHD1 inhibitor SOX11 has been identified as a therapeutic target in mantle cell lymphoma (MCL)." (PMID 41267084, 2025). "SOX11 has been described as a key oncogenic factor in mantle cell lymphoma (MCL)." (PMID 36551589, 2022). "SOX11 has been recognized as a major oncogene in mantle cell lymphoma." (PMID 35145272, 2022). "Additionally, the interaction between miR-223 and SRY-box 11 (SOX11) has gained importance in research towards treating Mantle Cell Lymphoma (MCL) and inflammatory diseases." (PMID 34239357, 2021). "SOX11, the locus which maps to the short arm of chromosome 2, which is often gained together with MYCN amplification in high-risk neuroblastoma, is a key oncogenic factor in multiple cancer entities including mantle cell lymphoma." (PMID 34638267, 2021). "In comparison with other B-cell lymphomas, mantle cell lymphoma has a poorer prognosis, and positive immunochemical staining of cyclin D1 and SOX-11 is useful for differentiating mantle cell lymphoma from other appendiceal lymphomas and treating patients appropriately." (PMID 34442137, 2021). "In addition, SOX11 is over-expressed in small cell lung cancer although contradicting results have also been reported in ovarian cancer, mantle cell lymphoma and glioma." (PMID 30922366, 2019). "SOX11 is a transcription factor that plays an important role in mantle cell lymphoma development." (PMID 30922366, 2019). "However, contradicting findings of SOX11 have been reported in ovarian cancer, mantle cell lymphoma and glioma." (PMID 30922366, 2019).
mantle cell lymphoma (continued). "In addition, sox11 levels have been found to be elevated in certain cancers in particular, mantle cell lymphoma, medullablastomas, Burkitt lymphoma, and immature lymphocytic neoplasm." (PMID 26505998, 2015). "In mantle cell lymphomas that express SOX11, the promoter is generally unmethylated." (PMID 25880212, 2015). "SOX11 plays pivotal roles in lymphoblastic neoplasms, mantle cell lymphoma, and Burkitt lymphoma." (PMID 23506684, 2013). "SOX11 is aberrantly expressed not only in mantle cell lymphoma (MCL), but also in some Burkitt lymphomas." (PMID 38237141, 2024). "In addition, SOX11 has been found to be aberrantly expressed in mantle cell lymphoma, subsets of Burkitt lymphomas, lymphoblastic leukemias and hairy cell leukemias, though its role in lymphopoiesis remains unknown yet." (PMID 34996493, 2022). "Up-regulation of SOX11 has been reported in malignant glioma, medulloblastoma, mantle cell lymphoma (MCL), as well as subsets of Burkitt’s lymphoma, ovarian cancer and breast cancer." (PMID 25880212, 2015). "A distinction from follicular lymphoma (positive for CD10 and BCL6), mantle cell lymphoma (CD5, cyclin D1, and SOX11), and chronic lymphocytic leukemia (CD5, CD23, and LEF1) is needed." (PMID 35053607, 2022). "The specimens revealed mantle cell lymphoma, with immunohistochemistry stains positive for CD20, Bcl-2, cyclin D1, SRY-box transcription factor-11 (SOX-11), immunoglobulin D (IgD) and immunoglobulin M (IgM) but negative for CD3, CD5, CD10 and CD23." (PMID 34442137, 2021). "SOX11 is a transcription factor that is normally expressed in the fetal brain and has also been detected in some malignant tumors, including mantle cell lymphoma (MCL)." (PMID 31714947, 2019). "SOX11 have been proved to promote invasive growth and progression of DCIS cells and prevent cell differentiation in mantle cell lymphoma." (PMID 30134837, 2018). "We and others recently identified SOX11 as aberrantly expressed in mantle cell lymphoma (MCL)." (PMID 21124928, 2010). "In this study we found variable expression of SOX11, SOX4 and SOX12 mRNA in mantle cell lymphoma cell lines." (PMID 21124928, 2010). "The absence of CyclinD1 (−) and SOX-11 (−) ruled out mantle cell lymphoma, and TdT (−) excluded lymphoblastic lymphoma." (PMID 41179665, 2025). "Although traditionally considered a very aggressive lymphoma, two indolent variants are now recognized: in situ mantle cell neoplasia and leukemic, non-nodal mantle cell lymphoma (SOX11 negative), which shows a high prevalence of splenic involvement." (PMID 34898558, 2021). "Leukemic mantle cell lymphoma limited to the blood and bone marrow is characterized by a lack of SOX11, mild-moderate lymphocytosis, and interstitial low-level bone marrow involvement." (PMID 34256839, 2021). "It appears therefore that SOX11 expression is a highly specific biomarker for cyclin D1- negative mantle cell lymphoma." (PMID 26949534, 2016). "The negative CD5, CD23, and CD200 may exclude the diagnosis of chronic lymphocytic leukemia/small cell lymphoma, and the negative CD5, Cyclin D1, FMC7, and SOX-11 can exclude the possibility of mantle cell lymphoma." (PMID 38335376, 2024). "SOX11 is also highly characteristic of mantle cell lymphoma, but not specific." (PMID 37530792, 2024). "Mantle cell lymphoma (MCL) is an aggressive B-cell non-Hodgkin lymphoma (NHL) subtype characterized by overexpression of CCND1 and SOX11 genes." (PMID 36359790, 2022). "Mantle cell lymphoma (MCL) is an aggressive non-Hodgkin B-cell lymphoma typically expressing CD19, CD20, CD5, FMC-7, CyclinD1, and SOX-11 and harboring the IgH/CCND1 translocation." (PMID 30627460, 2018).
mantle cell lymphoma (continued). "However, for setting up SOX11, INSM1, and MEOX2 assays, tissues with the strongest expression were chosen, given the lack of weak expressing tissues and general need to identify strong expressing cells of mantle cell lymphoma (SOX11), neuroendocrine tumours (INSM1), and endothelium (MEOX2)." (PMID 37568909, 2023). "Mantle cell lymphoma (MCL) is characterized by monomorphic small to medium-sized lymphoid cells with irregular nuclei and the CCND1 translocation, originating from peripheral B lymphocytes of the inner mantle zone, CD5+, and SOX11+ in the classical form." (PMID 36358737, 2022). "The SRY (sex determining region Y)-box 11 (SOX11) transcription factor was recently discovered as a new marker in mantle cell lymphoma (MCL), expressed in both cyclin D1 positive and negative cases." (PMID 21124928, 2010). "Negative staining for cyclin D1/SOX11 and CD10/BCL6 is useful for distinguishing MALT lymphoma from mantle cell lymphoma and follicular lymphoma, respectively." (PMID 40831827, 2025). "CD5+ DLBCL can be differentiated from pleomorphic and blastoid mantle cell lymphoma (MCL) by the absence of cyclin D1 and SOX11." (PMID 39684922, 2024). "SOX11 and BCL1 negativity ruled out mantle cell lymphoma (MCL)." (PMID 40861583, 2025).